SIRT1 (sirtuin 1)
Diseases named in the same sentence as SIRT1 in open-access papers (continued):
Sharing a sentence is not in itself a finding about the gene and the disease.
breast cancer (continued). "SIRT1 expression and prognosis: In a study comparing TNBC to HR+ breast cancer subtypes, SIRT1 expression was significantly lower in TNBC." (PMID 41300302, 2025). "In the study, the tumour-suppressive effects of the SIRT1 inhibitor EX527 (selisistat) alone and in combination with paclitaxel (PAX) in different breast cancer cell lines and zebrafish xenograft models were investigated." (PMID 39935420, 2025). "Benzothiazole derivatives (7ab and 7ba) that inhibit SIRT1, SIRT2, and SIRT3 in MCF-7 breast cancer cells reduced cell proliferation with IC50 values of 11.4 μM and 9.6 μM." (PMID 41471349, 2025). "Overexpression of SIRT1 reversed the EMT process as well as the migration and invasion abilities of breast cancer cells induced by MDSCs." (PMID 41281644, 2025). "In our recent review, we discussed the dual roles of both SIRT1 and SIRT6 in breast cancer, highlighting the tumor-suppressing and tumor-promoting effects of SIRT1 and SIRT6 in breast cancer." (PMID 40214422, 2025). "It was concluded that resveratrol reverses doxorubicin resistance by upregulating SIRT1 and negatively influencing the β-catenin pathway in MCF-7/ADR breast cancer cells." (PMID 40001961, 2025). "Overall, SLC influences oxidative phosphorylation via the PDK1/PDHA1 and SIRT1/PGC-1α/NRF1/TFAM signaling pathways and downregulates the HER2 pathway, thereby ultimately inhibiting HER2-positive breast cancer progression." (PMID 41465397, 2025). "Given the dual roles of both SIRT1 and SIRT6 in breast cancer, functional studies involving the introduction of EVs expressing SIRT1 and SIRT6 to breast cancer cells are required to determine the definitive roles of both enzymes in breast cancer." (PMID 40214422, 2025). "For example, amurensin G, a potent inhibitor of SIRT1, results in the inhibition of FOXO1 and MDR1 protein levels in adriamycin-resistant breast cancer cells." (PMID 39479446, 2024). "In MCF-7 breast cancer cells, NMNAT1 interacts with the nuclear NAD+-consuming enzymes PARP1 and SIRT1 and supports their ribosylation and deacetylation activities, respectively." (PMID 38396769, 2024). "In the breast cancer MCF-7 cell line, sirtinol reduced SIRT1 expression and successfully promoted cell death, resulting in G1 phase cell cycle arrest and apoptotic cell death, as well as autophagic cell death." (PMID 39479446, 2024). "It was previously reported that the genic knock-out of SIRT1 reduced the proliferation, migration, and invasion of MCF-7 breast cancer cells." (PMID 36771230, 2023). "Our results are consistent with previous reports that SIRT1 suppresses EMT in cancer by deacetylating Smad4 and inhibiting TGF‐β signaling in breast cancer and oral squamous cell carcinoma." (PMID 37667739, 2023). "Several proteins have been reported to regulate Sirt1, namely the activator AROS (active regulator of Sirt1) and the inhibitors HIC1 (hypermethylated in cancer), Dbc1 (deleted in breast cancer), and HIV1 Tat." (PMID 37109478, 2023). "Our findings support further efforts to investigate these enzymes, especially ACLY, SIRT1, and SIRT6 for breast cancer diagnosis and therapy." (PMID 35203617, 2022). "Compound 3g, designed by Laaroussi and colleagues, proved to be an SIRT-1 and SIRT-2 inhibitor with cytotoxic effects on leukemia, colorectal, lung and breast cancer cell lines." (PMID 36080416, 2022). "Based on their findings, the authors concluded that SIRT1 deacetylates and stabilizes PRRX1 to inhibit breast cancer stemness and metastasis." (PMID 36291902, 2022). "Our previous studies demonstrated that the NuRD(MTA1)/CRL4B complex and the SIRT1/CRL4B complex promote stemness and EMT in breast cancer and pancreatic cancer, respectively." (PMID 35534547, 2022). "SIRT1 upregulated the activities of POLD1/p125 to aid the proliferation, migration, and invasion of MCF-7 breast cancer cells." (PMID 36291902, 2022).
breast cancer (continued). "BZD9L1 is another SIRT-1 and SIRT-2 inhibitor able to induce apoptosis in colorectal, leukemia, and breast cancer cell lines." (PMID 36080416, 2022). "Inhibition of SIRT1 with either EX-527 or SIRT1 siRNA resulted in the upregulation of c-Myc (a pro-oncogenic protein) and MTDH (an oncogenic protein) in MDA-MB-231 and BT-549 breast cancer cells." (PMID 36291902, 2022). "In human breast cancer tissues, FOXM1 protein expression level is highly correlated with that of SIRT1." (PMID 34680943, 2021). "This is consistent with the protumourigenic role of SIRT1 in inducing EMT in pancreatic cancer, hepatocellular carcinoma and gastric cancer, but discordant with its EMT inhibition in breast cancer, lung cancer and ovarian cancer." (PMID 34226501, 2021). "In the case of SIRT1, it promotes the phosphorylation of protein (DBC1) deleted in breast cancer 1, which increases its affinity for SIRT1, leading to SIRT inhibition." (PMID 33435263, 2021). "In addition, miR 125a-5p could increase SIRT7 and also raised apoptosis in lung cancer cells to rise their radiosensitivity and miR-22 suppresses cancerogenesis and enhances radiosensitivity of breast cancer cells by selecting SIRT1, supplying a hopeful therapeutic objective for breast cancer." (PMID 33705642, 2021). "This work gives new information on the expression of SIRT1 and SIRT2 levels in individuals in the case of radiotherapy in breast cancer patients." (PMID 33705642, 2021). "In estrogen receptor-positive breast cancer cells, resveratrol elevated NAD+/NADH, subsequently activated Sirt1, and in turn activated the AMP-activated kinase (AMPK), a key sensor of cellular energy levels." (PMID 33430318, 2021). "Sirtuin 4 (SIRT4) inhibits the expression of sirtuin 1 (SIRT1) by inhibiting glutamine metabolism, and SIRT1 promotes the deacetylation of H4K16 to regulate the stemness of breast cancer cells." (PMID 35004688, 2021). "This retrospective study analyzes the expression of TFEB, CARM1, SIRT1, and Beclin-1 and the methylation of PITX2 in breast carcinoma." (PMID 34663249, 2021). "Achari and colleagues established that miR-34c exerts the antitumor activity in breast cancer by several mechanisms including the G2/M cell cycle arrest and the suppression of BCL2 and SIRT1." (PMID 33396625, 2020). "On the other hand, when T47D breast cancer cells were treated with nicotinamide (NAM), a SIRT1 inhibitor, PR-responsive gene transcription was decreased in a dose-dependent manner." (PMID 33330467, 2020). "Such SIRT1 inhibition (pharmacological/siRNA) leads to PI3K/Akt dependent ERα inhibition and repressed estrogen-dependent breast cancer cell growth." (PMID 33330467, 2020). "In fact, evidence that supports both a tumor promoter and suppressor function of SIRT1 has been reported for TNBC and luminal breast cancer subtypes." (PMID 32245130, 2020). "Recently, SIRT1/ERK/FOXM1 axis is demonstrated to be a critical pathway for linking metabolism to invasion and metastasis in breast cancer." (PMID 33193750, 2020). "Rsv activates Sirt1, promotes tubulin destabilization and inhibits SPHK, thus making it a potential phytochemical for treatment strategies against breast cancer." (PMID 31817453, 2019). "In the present study, we demonstrated for the first time that RES reversed DOX‐resistance, inhibited migration capacity of breast cancer DOX‐resistant cells by modulating EMT phenotype and SIRT1/β‐catenin pathway." (PMID 30697969, 2019). "Previous studies have shown that patient breast cancer samples that co-express high levels of LSD1 and histone deacetylases (SIRT1, HDAC2) have decreased survival." (PMID 31534138, 2019). "RES reversed EMT properties of MCF7/ADR cells by modulating the connection between SIRT1 and β‐catenin, which provides a hopeful therapeutic avenue to conquer DOX‐resistance and thereby prolong survival rates in breast cancer patients." (PMID 30697969, 2019).
breast cancer (continued). "High protein and mRNA expression levels of SIRT1 in hormone receptor-positive and HER2 breast cancer subtypes demonstrate its oncogenic role." (PMID 30761005, 2019). "To investigate this finding further, we studied the relationships between FOXO3, SIRT1 and SIRT6 expression by immunohistochemistry in a cohort of patients of different breast cancer subtypes." (PMID 31357743, 2019). "In a breast cancer model, through its direct interaction with its mRNA targets CDK6, SIRT1 and Sp1, which are genes involved in senescence, miR-22 has been able to suppress tumor growth." (PMID 31640796, 2019). "This work aims to summarize present knowledge on the interplay between SIRT1 and ER/GPER for breast cancer onset and progression." (PMID 30319540, 2018). "Another study showed that SIRT1 downregulation or miR-34a upregulation inhibits cell proliferation and colony formation ability in the MCF-7 cell line, as well as in CD44+/CD24− breast cancer stem cells (BCSCs)." (PMID 30380732, 2018). "Regarding miR-34c, Achari and colleagues demonstrated that miR-34c exert tumour-suppressive effects in breast cancer through different mechanisms, such as induction of G2/M cell cycle arrest and suppression of the pro-survival factors BCL2 or SIRT1." (PMID 30533999, 2018). "Depletion of SIRT1 remarkably increases the number of ALDH1+ CSCs, elicits partial MET, and promotes lung metastasis by upregulating KLF4 in human and mouse breast cancer cells." (PMID 30038266, 2018). "The authors showed that SIRT1 has effects on breast cancer cell growth through promoting the activity of oncogenic PI3K/Akt signaling pathway in vitro, and that SIRT1 is positively correlated with the expression of P-Akt in vivo." (PMID 30380732, 2018). "A significant positive correlation (R = 0.38, P = 0.0012) between nuclear SIRT1 and PRRX1 was observed in breast carcinomas." (PMID 30038266, 2018). "High levels of SIRT1, as well as low expression of its direct regulator miR‐34a, have been identified in CD44+/CD24‐ breast cancer stem cells (BCSCs)." (PMID 28994177, 2017). "Knockdown of SIRT1 mimicked the effects of resveratrol and pterostilbene on inhibition of SIRT1 in terms of the effects on telomerase and gamma-H2AX expression in HCC1806 breast cancer cells." (PMID 28611316, 2017). "The impact of H2S on NAMPT/SIRT1, likely, has global effects since it has been shown that RNA-mediated knockdown of NAMPT or NMNAT-1 in MCF-7 breast cancer cells reduced total cellular NAD+ levels and globally altered pattern of gene expression." (PMID 27732642, 2016). "A recent study reported that reductions in the levels of Sirtuin 1 (SIRT1), a highly conserved NAD-dependent deacetylase, in breast cancer and kidney tubular epithelial cells promoted tumor metastasis and kidney fibrosis, respectively." (PMID 27127545, 2016). "Hence, GPER targets SIRT1 as ERα toward cell survival and tumor growth, suggesting that appropriate combination therapies could offer more effective interventions according to the ER expression pattern in breast cancer." (PMID 26225773, 2015). "We show that HNK increases the expression of SIRT1 and SIRT3 and overexpression of SIRT1 and SIRT3 increases the cytoplasmic localization of LKB1 in breast cancer cells." (PMID 26359358, 2015). "As the regulation of SIRT1 has not been investigated in cancer cells lacking ER, in the present study we ascertained the expression and function of SIRT1 by estrogens in ER-negative breast cancer cells and cancer-associated fibroblasts obtained from breast cancer patients." (PMID 26225773, 2015).
breast cancer (continued). "It was also reported that miR-34a inhibits proliferation, migration, and invasion of breast cancer cells by targeting several genes including E2F3, CD44, and SIRT1, Notch1 and DLL1." (PMID 25826085, 2015). "The expression relationship between SIRT1 and N1IC protein in 150 samples with breast cancer showed a significant inverse correlation (r = −0.166, p = 0.042) in statistical analysis." (PMID 25420528, 2014). "In summary, we showed that the combined expression level of LSD1, HDAC2 and SIRT1 is a good predictor for OS and RFS in breast cancer patients." (PMID 25139823, 2014). "SIRT1, N1IC, and Snail were all found to be highly expressed and an inverse correlation between SIRT1 and N1IC in breast cancer tissue." (PMID 25420528, 2014). "Therefore, the definitive role of SIRT1 in breast cancer prognosis remains unclear." (PMID 25420528, 2014). "We measured the protein expression of SIRT1, N1IC, and Snail in 150 patients with breast cancer and matched adjacent normal breast tissues." (PMID 25420528, 2014). "More important, we need further to evaluate the impacting prognosis of SIRT1 and N1IC expression level (high vs. low) and the two markers expression pattern (combined vs. alone) in breast cancer tissues." (PMID 25420528, 2014). "We performed the correlation analysis between the expression of SIRT1, N1IC, Snail, and clinicopathological variables in 150 breast cancer patients." (PMID 25420528, 2014). "The purpose of this study was to assess the possible prognostic value of SIRT1, N1IC, and Snail expression in breast cancer patients." (PMID 25420528, 2014). "To this end we examined the immunohistochemical expression of SIRT1, N1IC, and Snail and analyzed their prognostic significance in breast carcinoma." (PMID 25420528, 2014). "Univariate Cox regression analysis was performed to analyze the relationship between SIRT1, N1IC, Snail expression, clinicopathological features and OS and DFS in 122 breast carcinoma patients." (PMID 25420528, 2014). "SIRT1 protein levels in both MCF7 and MDA-MB-231 breast cancer cells were reduced via retroviral infection with a pSuper-retro-RNAi construct encoding short hairpin loop RNA (shRNA) specific for “knocking down” SIRT1." (PMID 16596166, 2006). "Pan-SIRT1–3 inhibitor NH4-6 and SIRT2-selective inhibitor NH4-13 both suppressed tumor growth, but NH4-13 had lower toxicity and comparable efficacy in a breast cancer model." (PMID 41471349, 2025). "While its involvement in modulating response to HER2-targeted therapies like neratinib and lapatinib suggests its potential as a therapeutic target, further research is needed to fully elucidate SIRT1’s functions and to develop strategies for its modulation in HER2+ breast cancer treatment." (PMID 41300302, 2025). "The dietary phytochemical coumestrol, a known inhibitor of SIRT1–3, demonstrated significant reduction in cell proliferation and colony formation in MCF-7 and MDA-MB-231 breast cancer cells, accompanied by decreased SIRT1 expression and elevated intracellular ROS levels." (PMID 41471349, 2025). "Furthermore, full-length SIRT1 overexpression counteracted miR-155-5p-induced migration, invasion, and EMT marker modulation in breast cancer cells." (PMID 41281644, 2025).
breast cancer (continued). "DBC1, a tumor suppressor originally identified as a protein not expressed in breast cancer cells, binds to SIRT1 and inhibits its enzymatic activity." (PMID 38443596, 2024). "In contrast, in breast cancer with positive expressions of both hormone receptors but without Her2 expression, low SIRT1 expression is a marker of poor prognosis." (PMID 37762053, 2023). "As in breast cancer, there is currently no study demonstrating the tumor-promoting effect of miRNAs via the SIRT1 axis in prostate cancer." (PMID 36291902, 2022). "The roles of the SIRT1/FoxOs pathway in breast cancer and its metastasis have not been explained to date." (PMID 36142156, 2022). "Additionally, another study demonstrated that the knock-out of SIRT1 by shRNA reduced the proliferation, migration, and invasion of MCF-7 breast cancer cells." (PMID 36291902, 2022). "Additionally, overexpression of NNMT increased the levels of sirtuin 1 (SIRT1) in prostate and breast cancer cells, eventually promoting cell migration, invasion, and enhancing chemoresistance of cancer cells." (PMID 35338115, 2022). "Given the well-documented direct interaction between SIRT1 and RSV, a cellular thermal shift assay (CETSA), a label-free method to assess target binding to compounds in the native cellular environment, was performed in MCF7 breast cancer cells." (PMID 35821533, 2022). "Moreover, miR-200a suppressed cell proliferation in breast cancer by targeting mitochondrial transcription factor A16, and impaired EMT-like transformation, thus migration, by regulating SIRT1 in breast epithelial cells." (PMID 33536459, 2021). "In addition, we found that the combined LUT and I3C also synergistically reduced the expression of SIRT1 in MCF7 and T47D cells, which has been proved essential for oncogenic signaling by estrogen/ERα in ER+ breast cancer." (PMID 33925607, 2021). "Therefore, it shows biological roles that SIRT1 and SIRT2 play in the human organism in connection with radioactivity therapy during breast cancer treatment." (PMID 33705642, 2021). "This study’s main objective is to assess the prognostic role of TFEB, CARM1, SIRT1, and Beclin-1 in chemo-treated breast carcinoma and compare the TFEB, CARM1, SIRT1, and Beclin-1 expression with the methylation of PITX2 in breast cancer treated with chemotherapy." (PMID 34663249, 2021). "In other words, this present article discusses whether radioactivity has an activating or inhibiting effect on individual SIRT1 and SIRT2 proteins in breast cancer." (PMID 33705642, 2021). "As it was also observed with the present study and the debatable duties of SIRT1 and SIRT2 in cancer; it could be thought that more examination on the appearance proportion of soluble SIRT1 and SIRT2 proteins in human (breast) cancer needs to be done." (PMID 33705642, 2021). "To test this hypothesis, we used breast cancer cell lines (MCF-7 and MDA-MB-231), and we analyzed the expression of HIF-1α, PDK1, PDH, SIRT1, SIRT3, and ROS for mitochondrial metabolic pathway." (PMID 34771733, 2021). "Such compounds were evaluated in p300, PCAF, SIRT1/2, EZH2 and CARM1 enzyme assays, and in NB4 APL, U937 AML, MCF-7 breast cancer and SH-SY5Y neuroblastoma cells, to determine their effects in cell cycle phases and apoptosis induction when used at 5 μM for 30 h." (PMID 32650558, 2020). "In breast cancer, we have found that NNMT and its product 1MNA can inhibit the mitochondrion-mediated apoptosis through decreasing intracellular ROS, which enhances the resistance to chemotherapy by SIRT1 protein stabilization." (PMID 32489327, 2020).